FASN (fatty acid synthase)
Diseases named in the same sentence as FASN in open-access papers (continued):
Sharing a sentence is not in itself a finding about the gene and the disease.
breast cancer (continued). "The potential of neutraceuticals such as green tea polyphenol epigallocatechin-3-gallate (EGCG) and other flavonoids against breast cancer through downregulating the FASN activity has been suggested by previous studies." (PMID 31030489, 2019). "Oleuropein aglycone (OA) identified as the most in vitro potent EVOO phenolic against HER2-dependent breast cancer cell viability by selectively triggering high levels of apoptotic cell death and suppressing lipogenic enzyme fatty acid synthase expression." (PMID 30964898, 2019). "We analyzed the breast tissue sections of healthy subjects and breast cancer patients for the presence of FASN by immunofluorescence staining using anti-FASN antibody (unpublished results)." (PMID 30717356, 2019). "The oncogenic antigen-519, a molecular marker found in breast cancer patients with poor prognosis, was identified as FA Synthase (FASN) already twenty-five years ago." (PMID 31052427, 2019). "FASN is correlated with peritumoral lymphatic vessel invasion and inversely correlated with breast cancer survival." (PMID 30717356, 2019). "To characterize the possible effect of TQ on Her-2 over-expressed breast cancer cells, we determined the changes in the expression of FASN and Her2/neu in Her2+ and Her2- breast cancer cells." (PMID 31030489, 2019). "In 1994, FASN (known as antigen OA-519) was identified as a prognostic molecule for breast cancer patients with obviously poor prognoses." (PMID 31122252, 2019). "For instance, in vitro ectopic overexpression of FASN in breast cancer cells was found to promote lipogenesis along with augmented cell growth and proliferation." (PMID 31921669, 2019). "Abundant FASN expression was detected in breast cancer tissue sections compared to the normal healthy control tissue sections." (PMID 30717356, 2019). "We found that resveratrol constrained the growth of Her2 expressed breast cancer cells by inhibiting FASN in a dose dependent manner." (PMID 31030489, 2019). "The potential of nutraceuticals such as green tea polyphenol epigallocatechin-3-gallate (EGCG) and other flavonoids against breast cancer by downregulating the FASN activity has been suggested by previous studies." (PMID 31030489, 2019). "We previously reported the correlation of resveratrol-induced inhibition of cell proliferation with the status of FASN and Her2 expression in breast cancer cells." (PMID 31030489, 2019). "Knockdown of acetyl-CoA carboxylase 1 or fatty acid synthase disrupts fatty acids synthesis, acetyl-CoA and CoA production, and then induces apoptosis in breast cancer cells." (PMID 30388870, 2018). "Reports on breast cancer cells also support our suggestion that the inhibitory effect of EGCG on the FASN activity contributes to an inhibition of the CPT-1 activity." (PMID 29588626, 2018). "Subsequently, reduction of free fatty acid through inhibited FASN expression by cerulenin and C75 can induce a cytotoxic effect in the breast cancer cell line." (PMID 29588626, 2018). "FASN inhibitors have shown promising results for therapy of breast cancer and orthotopic tongue oral squamous cell carcinoma." (PMID 30283446, 2018). "Although this suggests FASN is an attractive therapeutic target in breast cancer, use of FASN-targeting drugs has been limited by serious side effects." (PMID 30140005, 2018). "Blockade of FASN leads to apoptosis in human breast cancer in vitro and in vivo and FASN inhibition after epigallocatechin-3-gallate (EGCG) treatment induced apoptosis in breast cancer cells." (PMID 29546056, 2018). "To improve the pharmacological profile of EGCG, we previously developed a family of EGCG derivatives and the lead compounds G28, G37 and G56 were characterized in HER2-positive breast cancer cells overexpressing FASN." (PMID 29751678, 2018). "Targeting fatty acid synthase (FASN) has shown that breast cancer models are highly-dependent on DNL for growth." (PMID 30140005, 2018).
breast cancer (continued). "A previous study demonstrated that the inhibition of the CPT-1 activity through knocking down the expression of FASN in breast cancer cells results in promoting an increase of ceramide levels." (PMID 29588626, 2018). "Our data raise concerns regarding targeting the FASN/ERα signalling pathway in ERα-positive breast cancers as inhibiting them enhanced the invasive potential of the cells via a novel caveolin-1-dependent mechanism." (PMID 29331414, 2018). "This line has lower constitutive FASN expression levels than the SK-Br3 HER2-positive breast cancer cell line against which compounds were previously screened." (PMID 29751678, 2018). "ACC and FASN are upregulated in HER2/neu-positive breast cancers at the transcriptional and the translational level in a HER2-amplicon or HER2-dependent manner, respectively." (PMID 29930756, 2018). "The PI3K/Akt inhibitor Ly 294,002, but not the ERK inhibitor PD 98059, inhibits the EGF-stimulated increase in m-SREBP-1 and FASN protein levels in MDA-MB-231 human breast cancer cells." (PMID 29282029, 2017). "Using pharmacological and genetic approaches, we assessed the molecular relationship between FASN signaling and estrogen receptor alpha (ERα) signaling in breast cancer." (PMID 28240737, 2017). "We thus conclude that FASN inhibition-promoted hyperactivation of ERα signaling exerts strong antitumor effects in hormone-dependent breast cancer cells." (PMID 28240737, 2017). "We and others have shown that silencing FASN using siRNA leads to improved sensitivity of breast cancer cells to chemotherapy." (PMID 29088813, 2017). "It has been reported that fatty acid synthase is overexpressed in PCa, breast cancer and pancreatic cancer, which is necessary for de novo fatty acid biosynthesis and malignant phenotype." (PMID 29245991, 2017). "Breast cancer cells show an increased activity of fatty acid synthase (FASN), an enzyme used for de novo fatty acid synthesis." (PMID 29163362, 2017). "We have shown that hyperglycaemia induces resistance to chemotherapy through upregulation of fatty acid synthase (FASN) in breast cancer cells and increased insulin-like binding protein 2 (IGFBP-2) in prostate cancer cells." (PMID 29088813, 2017). "FASN is lowly expressed or undetectable in most tissues but is overexpressed in a wide range of epithelial tumors, including breast cancer, because rapidly growing cancer cells require lipids for membrane synthesis and energy supply." (PMID 29093680, 2017). "We recently identified a new FASN inhibitor (Fasnall) that showed potent antitumor activity in a MMTV-Neu model of breast cancer." (PMID 28962653, 2017). "Fatty acid synthase (FASN), the major enzyme in de novo fatty acid synthesis, is highly expressed in breast cancer and its expression is reduced by polyunsaturated fatty acids (PUFAs) in liver." (PMID 29282029, 2017). "In the broader context of breast cancer cell lipid metabolism, most attention has focused on de novo lipogenesis from glucose and glutamine sources via increased expression of fatty acid synthase (FASN) and acetyl-CoA-carboxylase 1 (ACC1)." (PMID 28101337, 2017). "Previous studies in our laboratory have shown that IGFBP-2 is a novel regulator of the ERα, and that FASN and ERα overexpression in hyperglycaemic conditions contributes to chemo-resistance in breast cancer cells." (PMID 29088813, 2017). "A transcriptome analysis comparing HER2-positive with HER2-negative breast cancer cell lines demonstrated that expression of FASN was increased in cells that were HER2-positive." (PMID 28412757, 2017). "Together, these results demonstrate that suppression of FASN-driven endogenous lipogenesis is a novel upstream event regulating the MEK1/MEK2 → ERK1/ERK2 cascade in breast cancer cells." (PMID 28240737, 2017). "It is therefore important to distinguish the roles of DHA and AA in FASN protein expression in breast cancer." (PMID 29282029, 2017).
breast cancer (continued). "FASN inhibition suppressed E2-stimulated breast cancer cell proliferation and anchorage-independent colony formation while promoting the reduction of ERα protein." (PMID 28240737, 2017). "More importantly, these results reveal that FASN activity is a novel regulator of ERα signaling in hormone-responsive breast cancer cells." (PMID 28240737, 2017). "The FASN inhibitor attenuates the metastasis of different tumors, such as melanomas, breast cancer, oral cancer, and colorectal cancer." (PMID 29093680, 2017). "Glucose serves as a substrate for fatty acid synthase (FASN) and FASN is highly expressed in malignant cells including breast cancer." (PMID 29088813, 2017). "It was therefore of interest to know which signaling pathway is involved in FASN regulation by PUFAs in breast cancer." (PMID 29282029, 2017). "The inhibition of FASN can induce apoptosis in breast cancer cells through upregulating pro-apoptotic genes BNIP3, DAPK2, and TRAIL." (PMID 29093680, 2017). "Several studies have found FASN as a poor prognosis marker in cancers such as in lung, ovarian, gastric or in early breast carcinomas patients among others." (PMID 29088795, 2017). "Excitingly, we observed high expression of FASN in breast cancer cell lines in contrast to human mammary epithelial cells." (PMID 27270654, 2016). "For example, elevated levels of FASN, the major enzyme responsible for fatty acid biosynthesis, are correlated with poor prognosis in breast cancer patients." (PMID 27223259, 2016). "In this study, we provided strong evidence to show that miR-15a-16-1 targets FASN and reduces breast cancer cell proliferation." (PMID 27713175, 2016). "ACACA and FASN are upregulated in HER2/neu-positive breast cancers at the transcriptional and the translational level." (PMID 27464732, 2016). "Our study revealed that increased FASN expression was accompanied by an active inflammatory COX-2 pathway in the breast cancer cells." (PMID 27270654, 2016). "OPG present in the breast cancer microenvironment has the significant potential to stimulate the transcription of FASN." (PMID 27270654, 2016). "In the present study, we show that CCN1 significantly stimulates FASN gene transcription and FASN protein accumulation in breast cancer cells." (PMID 27713913, 2016). "Immunofluorescence staining revealed the co-existence of COX-2 and FASN in the lipid bodies of breast cancer cells." (PMID 27270654, 2016). "Upregulation of FASN represents a nearly-universal phenotypic alteration in most human malignancies including breast cancer." (PMID 27579768, 2016). "We show here that loss of BRG1 attenuated FASN, ACC, and ACLY expression and impaired de novo lipid synthesis in breast cancer cells with a concomitant decrease in cell proliferation." (PMID 27223259, 2016). "For example, miRNA-195 suppressed the proliferation, invasion and metastasis of breast cancer cells via FASN, HMGCR, ACACA and CYP27B1." (PMID 27813492, 2016). "Overall, our data suggest that both miR-15a and miR-16-1 contribute to inhibiting FASN expression and breast cancer cell proliferation." (PMID 27713175, 2016). "In our recent study we demonstrated that compared to HMEC, SUM149PT and SUM1315MO2 breast cancer cells express increased level of FASN." (PMID 27072583, 2016). "Multiple studies indicated that FASN is a potential prognostic marker and therapeutic target of cancers, including breast cancer, while miR-15a-16-1 and miR-497-195 play a tumor suppressive role." (PMID 27713175, 2016). "Our results here show that the elevated levels of lipid synthesis found in breast cancer are dependent on BRG1 acting to upregulate the transcription of FASN, ACC, ACLY and other genes involved in fatty acid synthesis." (PMID 27223259, 2016). "Collectively these results for the first time show the co-existence of OPG, PGE2 and FASN in breast cancer tissues when compared to the control breast tissues sections." (PMID 27270654, 2016).
breast cancer (continued). "Approximately two decades ago, Swinnen and colleagues demonstrated that FASN expression is upregulated by androgens in LNCaP cells, an effect similar to progestins in breast cancer cells." (PMID 26934656, 2016). "To evaluate the transcriptional activity of PR receptors in BRCA1 mutated tissues, we examined the expression level of fatty acid synthase (FASN), a PR-induced target gene that is associated with tumor growth of breast cancer cells." (PMID 27246982, 2016). "This study serves as the basis for future studies designed to validate the in vivo anti-tumorigenic efficacy of COXIB and FASN inhibitor combination therapy in breast cancer models." (PMID 27270654, 2016). "Mass spectrometry analysis identified FASN as one of the binding partners for OPG in breast cancer cells." (PMID 27270654, 2016). "Compared to HMEC, breast cancer cells showed increased FASN and ACC1 protein levels in SUM149PT and SUM1315MO2 cells." (PMID 26621841, 2016). "Here we show that suppression of the lipogenic enzyme fatty acid synthase (FASN) leads to stable reversion of the malignant phenotype and normalizes differentiation in a model of breast cancer (BC) progression." (PMID 27223424, 2016). "The tumor-promoting effects of enhanced fatty acid synthesis were first appreciated in the 1990s when fatty acid synthase (FASN) expression was identified as prognostic marker of aggressive breast cancers." (PMID 27635066, 2016). "Our study revealed the superior anti-proliferative role of COX-2 inhibitor celecoxib and FASN blocker C75 in aggressive breast cancer cells." (PMID 27270654, 2016). "Curcumin, as well, induces apoptosis, inhibiting intracellular fatty acid synthase in human breast cancer." (PMID 27213347, 2016). "In this study, we investigated the anti-tumorigenic, anti-lipogenic, and anti-inflammatory potential of COX-2 inhibitor celecoxib and FASN blocker C75 on two specific breast cancer cell lines." (PMID 27270654, 2016). "Both miR-15a and miR-16-1 contributes to inhibiting FASN expression and breast cancer cell proliferation." (PMID 27713175, 2016). "In summary, our findings provide a rationale for the preclinical development of inhibitors of FASN activity in combination with anti-HER2 signaling agents in breast cancer refractory to anti-HER2 therapies." (PMID 26107737, 2015). "In serum, compound 23 and compound 30 are in equilibrium with their metabolites, which also displayed strong FASN activity inhibition, in particular compound 30 (83% of FASN activity inhibition in SKBr3 human breast cancer cells)." (PMID 25855977, 2015). "mRNA levels of FASN, the key enzyme in this process, were induced in breast cancer lines in response to 48 h of hypoxia, while FASN expression was observed to be reduced after 12 h hypoxia in HepG2 cells." (PMID 25605240, 2015). "Inhibition of FASN alters the expression of several ubiquitin ligases and ubiquitin conjugation enzymes in breast cancer cells, and stimulates ubiquitination and degradation of PI3K substrates in ovarian cancer cells." (PMID 26659560, 2015). "And, in breast cancer cell lines, C75 inhibited FASN and stimulated beta-oxidation through carnitine palmitoyltransferase-1 (CPT-1) regulation or directly suppressing HER2 and FASN phosphorylation." (PMID 26351511, 2015). "It was demonstrated that HIF1 induces the expression of FASN in human breast-cancer cell lines and that FASN expression is increased in hypoxic tumor regions." (PMID 26452259, 2015). "It has also been shown the synergism between mTOR and FASN inhibition to induce cytotoxicity in ER/HER2-positive breast cancer cell lines." (PMID 26107737, 2015). "FASN is the key enzyme involved in the regulation of cellular fatty acid synthesis and is highly expressed in many cancers such as lung cancer, breast cancer, prostate cancer, colon cancer and many other tumors." (PMID 25433947, 2015). "Blocking the enzyme Fatty Acid Synthase (FASN) leads to apoptosis of HER2-positive breast carcinoma cells." (PMID 26107737, 2015).
breast cancer (continued). "Consistent with this, OA-519 was identified in breast carcinomas, correlating with FASN activity and poor patient prognosis." (PMID 25605240, 2015). "Western blotting indicated that FASN was expressed at different levels in all three breast cancer cell lines; FASN expression was higher in HER2-positive cells, such as SKBR3 and MCF-7/HER2 cells, than in MCF-7 cells, which expressed lower HER2 levels." (PMID 24866893, 2014). "We evaluated FASN and mTOR expression in breast cancer cell lines by western blotting and indirect immunofluorescence." (PMID 24866893, 2014). "The identification of OA-519, a marker of poor prognosis in breast cancer, as fatty acid synthase two decades ago sparked new interest in this area of cancer metabolism." (PMID 24893952, 2014). "In breast cancer, FASN is found to be highly expressed in various breast cancer cell lines, including hormone-independent SKBR3 and hormone-dependent MCF-7 and ZR-75-1 cells." (PMID 24778702, 2014). "The transcriptional activity of the FASN promoter decreased in all three breast cancer cell lines in response to LY294002." (PMID 24866893, 2014). "What role do dietary fatty acids play in modulating the growth of mammary tumors that have reduced FASN activity?" (PMID 25472762, 2014). "In this study, FASN was identified as the key downstream effector in ER/HER2 crosstalk in ER+/HER2+ breast cancer cells." (PMID 24866893, 2014). "This work highlights the potential of studying molecules that influence FASN activity as contributors to tumorigenesis and as potential therapeutic targets for the treatment of breast cancer." (PMID 25472762, 2014). "The present study implicated the PI3K/AKT/mTOR pathway in the regulation of FASN expression in ER/HER2-positive breast cancer cells and demonstrated that rapamycin, an mTOR inhibitor, inhibited FASN expression." (PMID 24866893, 2014). "Since the 1980s, researchers have identified FASN in various cancers including breast cancer, colon cancer, prostate cancer, ovarian cancer, and endometrium cancer." (PMID 24778702, 2014). "Our results showed that the combination of the mTOR and FASN inhibitors potently inhibited the growth and invasive capacity of three breast cancer cell lines, even at low concentrations." (PMID 24866893, 2014). "We used a PI3K/AKT pathway inhibitor and an mTOR inhibitor to probe the role of the PI3K/AKT/mTOR pathway on FASN expression in ER+/HER2+ breast cancer cells." (PMID 24866893, 2014). "We used luciferase reporter assays to explore the effect of an mTOR inhibitor on FASN transcription in ER+/HER2+ breast cancer cells." (PMID 24866893, 2014). "In particular, Fatty acid synthase (FASN) is highly expressed in breast cancer with a poor prognosis compared to others." (PMID 25233347, 2014). "There have been years of research on FASN inhibitors and their role in breast cancer therapy in western medicine and recently Chinese Medicine has developed a similar research, with a focus on the weight loss effect of the inhibition of FASN using herbs." (PMID 24778702, 2014). "We further examined the transcriptional activity of the FASN promoter in the three breast cancer cell lines after treatment with LY294002 (25 μmol/L, 4 h)." (PMID 24866893, 2014). "FASN is expressed in most of cancer cells, for example, breast cancer cells, and has a low expression in normal cells." (PMID 24778702, 2014). "Reportedly, increased fatty acid synthase (FASN) activity has been shown in breast cancer cell lines, ovarian tumors, or cancer precursor lesions in different locations (colon, stomach, esophagus, and oral cavity)." (PMID 24829560, 2014). "The transcriptional activity of the FASN promoter was significantly higher than that of the SV40 strong promoter (pGL3-control as the positive control) in all three breast cancer cell lines, and especially in SKBR3 and MCF-7/HER2 cells." (PMID 24866893, 2014).